IL10 (interleukin 10)
Diseases named in the same sentence as IL10 in open-access papers (continued):
Sharing a sentence is not in itself a finding about the gene and the disease.
infection (continued). "In conclusion, we provide evidence for the induction of IL-10-associated apoptosis of CD4+ cells, which leads to the development of hyporesponsiveness in the lymph nodes draining the site of infection shortly after exposure to repeated doses of infective schistosome parasites." (PMID 25624353, 2015). "Additionally, PPD-specific Th2 cytokines (IL-5 and IL-10) were consistently induced after Mtb K infection compared to Mtb H37Ra and H37Rv infection." (PMID 26675186, 2015). "Interestingly, IL-10 was strongly induced in a dose-dependent manner upon infection with N. gonorrhoeae." (PMID 26125939, 2015). "Thus, TLR4 can upregulate the expression of cytokines, such as TNF-α, IFN-γ, IL-6, IL-8, IL-12, and IL-10, thereby increasing resistance to pathogen invasion and infection." (PMID 26576220, 2015). "However, we observed a higher percentage of IL-10+ cells when cultures were infected by Col cl.1.7, compared to infection by the Y strain." (PMID 26147698, 2015). "In conjunction with NOD/CARD intracytoplasmic proteins, TLRs mediate signals to key transcription factors including NF-κB to activate pro-inflammatory and anti-inflammatory cytokines (IL10) which regulate the innate and adaptive immune response for the efficient clearance of infection." (PMID 26482908, 2015). "Moreover, Pam3CSK4 treatment enhanced IL-10 release both in vivo and in vitro, whereas Ad-siTLR2 infection suppressed IL-10 secretion." (PMID 26475712, 2015). "IL-19, IL-10, IL-6, IL-27 and IL-5 also increased during late infection days." (PMID 26070790, 2015). "Daily survey of A. butzleri loads in fecal samples revealed that following infection with 109 viable A. butzleri strains CCUG 30485 or C1, gnotobiotic IL-10-/- mice could be stably colonized with pathogenic loads of 108 CFU per gram fecal sample." (PMID 26406497, 2015). "Instead, only CD4+ Foxp3− IL-4+ Th2 cells showed increased IL-10 production upon infection." (PMID 26195548, 2015). "Based on our computed results, we concluded that a Healing Process occurs when the level of pathogens, level of phagocytic cells (neutrophils and monocytes), and level of inflammatory cytokines (TNF-α, HMGB-1, and IL-10) oscillate below threshold during infection." (PMID 26446682, 2015). "Similar results were obtained if IL-10 was neutralized at the time of infection, suggesting that B cells producing IL-10 might modulate immune response in filarial-infected mice, via the suppression of CD80 and CD86 expression on Bregs." (PMID 26236565, 2015). "Based on simulated results from our SDMM, we inferred that the survival rate of the host (chance of ending with a Healing Process) could be improved if a medium level of IL-10 injection was set between 3 hrs and 6 hrs after infection." (PMID 26446682, 2015). "However, one day after infection, the proportion of IL-10 producing cells was equally split between CD4+ T cells and F4/80+MHC-IIhigh macrophages." (PMID 25974019, 2015). "Using B-1CDP cells from IL-10 KO mice the infection with L. major was less effective." (PMID 25933287, 2015). "In this study T. b. brucei-infected mice were systemically treated with recombinant murine IL10 to test the hypothesis that treatment would reduce pathology and CNS parasite load in a highly defined model of late stage infection." (PMID 26505761, 2015). "Interestingly, serum from infected Mir155-/- mice had very low IFNγ levels, compared to serum from the other three strains at 4 weeks post-infection, and infected Il10-/- mouse serum had very high IFNγ levels, compared to serum from the other three strains." (PMID 26252010, 2015). "In addition, a shift in T helper cell polarization toward Th2 and Treg cells was observed 5 days post-infection, and the mRNA expression of the anti-inflammatory cytokine Il10 was markedly increased at day 7 post-infection." (PMID 26230498, 2015).
infection (continued). "TB-IRIS may either be “unmasking” (of an occult infection) or “paradoxical” (worsening of a known infection during retroviral treatment) hyper-inflammation: decreased serum IL-10 levels were found in paradoxical compared to unmasking syndromes." (PMID 26029205, 2015). "The production of IL-10 increases substantially in the skin site of infection, especially after repeated exposure to cercariae, and is responsible for the induction of CD4 T cell hyporesponsiveness in the skin draining lymph nodes and prevention of excessive tissue damage/inflammation in the skin." (PMID 26116503, 2015). "In order to determine if Mir155 was upregulated in heart and skin tissue, infected B6 and Il10-/- mice with B. burgdorferi were analyzed at 3 weeks post-infection, a time point consistent with the peak for NF-κB dependent responses in B. burgdorferi-infected mice." (PMID 26252010, 2015). "However, it has recently become clear that effector CD4+ T cell production of IL-10 plays an important role in limiting host pathology and promoting chronicity of infection." (PMID 26417443, 2015). "In addition, experimental infection revealed significant elevation in the expression of tnfalpha, il1alpha, cox2, and il10 in the blood of dead hamsters compared with that of the survivors." (PMID 26146835, 2015). "In addition early transient induction of IL-10 as well as B cells have been observed following experimental infection in conjunction with IFN-γ as an early marker of infection." (PMID 26092382, 2015). "IL-2 can enhance host immunity and inhibit parasitic growth, inducing a Th1-type immune response; by contrast, IL-10 inhibits cytokine production by Th1 cells while exhibiting increased serum levels with infection progression, resulting in mainly Th2-type immune response." (PMID 26352932, 2015). "Moreover, skin-resident tissue macrophages, which encounter S. mansoni excretory/secretory products during infection, are the first monocytes to produce IL-10 in vivo early postinfection with S. mansoni cercariae." (PMID 26116503, 2015). "GM-CSF synergises with IFN-γ in reducing IL-10 synthesis by macrophages in response to infection." (PMID 25706389, 2015). "The higher values of the IL-10/ IFN-γ ratio obtained in control groups suggest that the members of the LiPABP family may be acting as an anti-inflammatory stimulus during infection." (PMID 25955652, 2015). "IL-10 has been called the master regulator of immunity to infection." (PMID 26252010, 2015). "The role of IL-10 has also been observed upon infection with other pathogens." (PMID 26125939, 2015). "In contrast, the expression of IL-10 increased beginning 3 dpi after Ts infection." (PMID 25803101, 2015). "Interestingly, in this study, the expression of IL-10 in monocytes was the only parameter that allowed for distinguishing between the two strains, where we observed a higher IL-10 expression after infection with Col cl1.7 compared to infection with Y strain." (PMID 26147698, 2015). "In addition, a relevant change in the profile of cytokine expression was observed in relation to the acute phase of infection, with IL10 being switched on and IFNγ off." (PMID 25890318, 2015). "We also investigated a potential association between intensity of infection (worm burden) and IL-10 levels, but none was found." (PMID 25888883, 2015). "In contrast with cerebellar IL-6, IL-10 concentrations were significantly increased in mice with high vitamin D3 supplementation that died during the acute phase of the infection compared with the animals that had received low or standard vitamin D3 supplementation (*P < 0.05)." (PMID 25563481, 2015). "The FeD mice also had increased concentrations of TNFα and IL-10 after infection." (PMID 25768944, 2015).
infection (continued). "Conversely to what has been shown for E75CV1 the progression of the E75-infection resulted in a dramatic imbalance of the immune system by day 7 pi, with the significant up-regulation of 9 genes, namely: IL-5, IL-1β, IL-6, IL-8, IL-10,IL-21, IL-23, DEFB2 and TLR-3." (PMID 26589145, 2015). "IL-10 mRNA levels were raised p.i. in group A, and antibodies to rDnaK were also detected in this group, indicating some Th2 response activity following de novo infection." (PMID 25410206, 2015). "There is evidence that FcγR might help to produce anti-inflammatory cytokines such as IL-10 and TGF-β that play a role in susceptibility to infection." (PMID 26693244, 2015). "The IL-10 production is high during the infection promoting reactivation of TB." (PMID 26359865, 2015). "IL10 could be amplified only from samples collected from infected fish at the late stage of infection stage." (PMID 26397117, 2015). "Since Tregs and IL-10 may contribute to persistence of an infection with H. suis, we hypothesized that CCR4 antagonists might help to induce protective immunity." (PMID 26115373, 2015). "There was a peak of cytokines IL-10, IL-13, IL-6 and IL-4, 17 weeks after infection." (PMID 24886277, 2014). "Consequently, over time changes in the IP-10/IL-10 ratio for one individual will provide relevant clinical information with respect to the outcome of infection." (PMID 24810599, 2014). "IL-10 expression was elevated after 8 and 24 hours of infection." (PMID 25105760, 2014). "After 6 hours of infection, the increase of IL-10 may signal the beginning of a “return to normal” and down-modulation of the immune response." (PMID 25118595, 2014). "Here by using the galactosyl transferase knock down parasite (KD-SbR-LD) we got the level of IL-10 almost close to the amount we observed in infection with SbS-LD, which indicates towards a possible role of this glycan in the observed differential immune response." (PMID 25032977, 2014). "A high IL-4 response coinciding with enhanced IgG1 correlated with a failure of protection in alum + LAg immunized mice, whereas exacerbation of infection in saponin + LAg immunized mice may involve the unbalanced secretion of IL-4 in conjunction with IL-10." (PMID 24428931, 2014). "Thus, the regulation of IL-10, IL-19 and IL-24 expression in filarial infection is dependent on the presence of active infection and therefore, curative treatment ablates the increase in the frequency of these predominantly regulatory T cells." (PMID 24699268, 2014). "In contrast, IL-10 and IL-12 levels were lower in CPEfat/fat mice 48 h post-infection." (PMID 25203099, 2014). "The splenocytes of vaccinated hamsters receiving liposomal rCPC and cocktail of three liposomal CPs showed higher IFN-γ, IL-2, TNF-α and IL-12 mRNA expression than all other groups but appreciable downregulation of macrophage deactivating cytokines like IL-4, IL-10 mRNAs, before and after infection." (PMID 25144181, 2014). "Notably, rPCN administration on the days 3 and 10 after infection enhanced both Th1 immunity and IL-10 production." (PMID 25474158, 2014). "Splenocytes from ST2 deficient mice had no impaired production of IL-4, IL-5, IL-10 or IFNγ following ConA stimulation and this was throughout infection." (PMID 24663956, 2014). "Therefore, our study suggests that different TLRs regulate IL-10 expression in different ways, perhaps allowing the fine-tuning of IL-10 production to suit infections with different pathogens and/or commensals." (PMID 24227629, 2014). "At 48 h post-infection, the lower levels of IL-10 and IL-12 and trend for reduced TNF-α in CPEfat/fat mice may have been due to the non-significant trend for lower spleen CFUs." (PMID 25203099, 2014). "IL-10 is often considered as the master regulator in immunity from infection." (PMID 24565171, 2014).
infection (continued). "There is also evidence for IL-10 as a factor in humans with active TB, where IL-10 mediates inhibition of antigen presentation to T cells, and therefore mediates a decreased ability to clear infection contributing to TB pathogenesis." (PMID 24715893, 2014). "However, pre-treatment with the IL-10 neutralizing antibody prior to Mycobacterium tuberculosis H37Rv infection exhibited a sharp decline in STAT-3 binding at CCR5 locus in infected macrophages." (PMID 24695099, 2014). "Primary genital C. suis infection of the re-infection group (nine-week-old pigs) resulted in increased secretion of TNF-α, IL-1β, IL-6 and IL-12p40 by PBMC, whereas primo-infection of the infection group (seventeen-week-old animals) decreased the IL-1β, IL-8 and IL-10 secretion by PBMC." (PMID 25252649, 2014). "Reduced IL-10 transcripts in response to infection with the flaA mutant were observed as early as 1 hour post-infection; this difference gained significance 6 hours post-infection (P < .05)." (PMID 24823621, 2014). "However, identities of the distinct cell types contributing to higher IL-10 in drug resistant LD infection remain elusive." (PMID 25032977, 2014). "Taken with our data on expression of IL-10, it appears that regulation of responses through T regulatory lymphocytes is key to both maintaining a healthy gut and reducing colonization by C. jejuni following infection." (PMID 24987092, 2014). "Thus, the frequency of T cells expressing IL-10, IL-19, IL-24 and IL-26 are all decreased upon curative treatment, in contrast to that seen in those who continued to harbor infection." (PMID 24699268, 2014). "The data we present here showing both elevated IL-10 expression in infected (versus virally exposed or naïve) CD8αneg DCs together with the finding that these cells are able to induce IL-10 expression in naïve CD4 T cells likely explains how infection of CD8αneg DCs contributes to total IL-10." (PMID 24613988, 2014). "In addition, Tregs often express IL-10 at sites of infection/inflammation, which can minimize host tissue damage but also allows parasites or viruses to evade effector responses and proliferate." (PMID 24841130, 2014). "The lower accumulation of inflammatory monocytes in Mif−/− mice at this stage of infection could result from the reduced expression of Ccl2 and/or increased production of IL-10." (PMID 25255103, 2014). "However, a strong correlation between elevation of IL-6 and IL-10 and severe pH1N1 infection was noted." (PMID 25003343, 2014). "We also identified specific subsets of APCs from various anatomical sites responsible for the expansion of γδ T cells with suppressive function and show that in vitro infection of APCs with modified vaccinia Ankara (MVA) increased the frequency of IL-10–expressing γδ T cells." (PMID 24890724, 2014). "Likewise IL-10 levels were shown to be significantly higher in naïve mice exposed to saliva during infection (estimate 0.8398, p value<0.001)." (PMID 25275509, 2014). "Infection by viable chlamydia could only induce secretion of IL-10 in monocytes, indicating that an active infection is essential for inducing these particular cytokines in monocytes or DCs." (PMID 25123797, 2014). "Since S. Typhimurium is an intracellular pathogen that resides within macrophages during infection, IL-10 produced by macrophages might act locally on tissue macrophages to generate a more permissive niche for intracellular S. Typhimurium infection." (PMID 24787713, 2014). "Indeed, epithelial cells responded early to mycobacterial infection by secreting IL-6 and the anti-inflammatory IL-22, while the anti-inflammatory IL-10 increased two days after infection." (PMID 24489729, 2014). "FP thickness in IL-10−/− was greater than in B6 mice throughout infection (p<0.05)." (PMID 25210773, 2014).
infection (continued). "It was found that the expression of regulatory cytokines like Tgf-β and IL-10 is an important feature in the course of parasitic infections because the immunological down-modulation during an infection can protect the host from pathological outcomes of the infection." (PMID 25372668, 2014). "Here we investigated whether IL-10 was responsible for the regulation of MHC-II expression in macrophages during H37Rv infection." (PMID 24695099, 2014). "PBS57-treated mice also showed higher IL-10 levels 3 days post infection." (PMID 24967701, 2014). "The authors hypothesize that MAPK p38 and ERK 1 pathways with respect to TNF-α production, as well as the MAPK p38 and ERK 1 and 2 pathways in relation to IL-10 production under infection by C. pseudotuberculosis are important regulators of cellular response." (PMID 25179342, 2014). "Interestingly, IL-10 is also generated at low levels after infection as a part of effector response to prevent autoimmunity and maintenance of T cell proliferation." (PMID 25144181, 2014). "Infection of burn mice, regardless of bacterial strain, caused an elevation of serum IL-10 compared to sham mice." (PMID 24454904, 2014). "Infection induced a significant IL-6 and IL-10 secretion that peaked at 72 hours." (PMID 24489729, 2014). "Additionally, IL-10 and IL-12a mRNA levels were significantly reduced in the LPi mice due to the interaction between low protein diet and infection (p<0.01)." (PMID 25535967, 2014). "However, a remarkable increase in the expression of IL-10 was observed 8 weeks after infection and maintained at a high level at 13 weeks." (PMID 24666892, 2014). "In contrast, at the resolution phase of infection, IL-10 level was slightly increased in SOCS1−/−IFN-γ−/− mice relative to the low levels in WT and IFN-γ−/− mice, which may contribute to the attenuation of lung inflammation after viral clearance." (PMID 25500584, 2014). "Importantly, infection with an 81-176 flaA mutant showed comparable reduction in IL-10 when compared to its WT counterpart, suggesting this phenomenon was not specific to the 11168H WT strain." (PMID 24823621, 2014). "In the late phase of infection (on days 19 and 26), 5-LO−/− spleen cells, in contrast to what was observed for WT spleen cells, showed a sustained elevation in the production of IL-1β and IL-10, higher levels of IL-12, and lower levels of IFN-γ." (PMID 25165415, 2014). "However, CD4 T cells can also contribute to immunosuppressive effects including IL-10 production which limits the induction of protective Th1 responses and promotes prolonged infection of the SG." (PMID 25120535, 2014). "Thus, deficiency of the cj0268c gene did not impact gastrointestinal colonization capacities of C. jejuni in gnotobiotic IL-10−/− mice upon peroral infection." (PMID 24587249, 2014). "Recently, rapid expansion of Tregs associated with an increased expression of the immunosuppressive cytokine IL-10 has been demonstrated in the brain of susceptible SJL mice but not in resistant C57BL/6 mice following TMEV infection." (PMID 25391297, 2014). "The direct correlation of IL-10-producing B cell frequency with viral load in EI suggests that IL-10-producing B cell may contribute to HIV-1 persistence in the early stages of infection, by suppressing immune responses as previously shown in other infections." (PMID 24586620, 2014). "In this study, IL-10 was produced only in response to infection." (PMID 25386119, 2014). "TNF-α and IL-10 expression exhibited a significant increase at the peak of infection." (PMID 24991553, 2014). "Likewise, IL-12p40 and IL-10 mRNA were expressed at similar levels in the livers of IL-4Rαflox/Δ littermate controls and IL-4Rαflox/ΔLysMCre mice at 9 and 16 weeks post-infection." (PMID 25211233, 2014). "Thus, enhanced IL-2, IL-12, TNF-α and IFN-γ mRNA expression but downregulation of IL-10, most remarkable in cocktail vaccinated hamsters is chiefly responsible for strong Th1 biased immunity after infection." (PMID 25144181, 2014).